CDK5 (cyclin dependent kinase 5)
Diseases named in the same sentence as CDK5 in open-access papers (continued):
Sharing a sentence is not in itself a finding about the gene and the disease.
medullary thyroid carcinoma (continued). "STAT3 activation status showed similar activation status with CDK5, suggesting that STAT3 activation might be CDK5-dependent in GDNF-induced medullary thyroid cancer cell proliferation." (PMID 34207842, 2021). "Besides, our previous study demonstrated that CDK5 phosphorylates STAT3 in prostate and medullary thyroid cancer cells." (PMID 34207842, 2021). "Overall, our data reveal that CDK5 activation occurs after RET activation by GDNF stimulation, suggesting that CDK5 may be a potential downstream of RET protein in GDNF-induced human medullary thyroid cancer cell proliferation." (PMID 34207842, 2021). "Since CDK5 and RET have been reported to play an essential role in human medullary thyroid cancer cell proliferation, we next hypothesized that there might be some regulation between CDK5 and RET proteins." (PMID 34207842, 2021). "Since CDK5 has been reported to play an essential role in various types of cancer cells, including medullary thyroid cancer cells, this study aimed to investigate the role of RET-mediated CDK5 activation and their interaction in GDNF-induced human medullary thyroid cancer proliferation." (PMID 34207842, 2021). "Since we have previously reported that CDK5 phosphorylates STAT3 at Ser727 site in prostate and medullary thyroid cancer cells, thus, we thought that STAT3 might be a potential downstream of CDK5 in GDNF-induced RET signaling in medullary thyroid cancer cell proliferation." (PMID 34207842, 2021).
cervical cancer (9 papers, 2015 to 2021). A primary or metastatic malignant neoplasm involving the cervix. "Our previous results demonstrated that hyperactivation of CDK5 would cause apoptosis of prostate and cervical cancer cells." (PMID 31395805, 2019). "In post-transcriptional level, microRNA-505-5p functions as a tumor suppressor by targeting CDK5 in cervical cancer." (PMID 35006426, 2021). "We also illustrated that RA induces apoptosis in cervical cancer cells through the hyperactivation of CDK5." (PMID 31395805, 2019). "To date, no study has been available to investigate the expression and clinicopathological significance of CDK5 expression in cervical cancer tissues." (PMID 27406233, 2016). "In this study, we primarily used IHC method to detect the expression of CDK5 in cervical cancer tissues and precancerous lesions, and analyzed its potential role in the tumor genesis of cervical cancer." (PMID 27406233, 2016). "Further, the results showed that higher CDK5 expression in cervical cancer with lymph node metastasis has some similarities with studies in other malignancies." (PMID 27406233, 2016). "Though expression of CDK5 was detected in cervical cancer tissue and regulative mechanism of CDK5 was investigated in other cancers, the probable mechanism between CDK5 and lymph node metastasis in cervical cancer still needs further confirmation." (PMID 27406233, 2016). "In this study, we investigated the differential expression level of CDK5 in patients with cervical cancer and precancerous lesions so as to clarify the correlation between CDK5 and carcinogenesis and progression of cervical cancer." (PMID 27406233, 2016). "Statistically analysis showed that CDK5 expression in cervical cancer tissues was higher than non-cervical cancer tissues (inflammation and CA) (P < 0.001)." (PMID 27406233, 2016). "In summary, the present study confirmed a higher expression level of CDK5 in cervical cancer tissues compared with precancerous lesions." (PMID 27406233, 2016). "A study reported that CDK5 had a role in decreasing the growth of human cervical cancer cell line when retinoic acid treatment was applied to use and the expression of CDK5 and p35 were up-regulated by retinoic acid treatment." (PMID 27406233, 2016). "Interestingly, CDK5 was also shown to be activated by binding to cyclin I in cisplatin-resistant cervical cancer cells, where cyclin I–CDK5 complex was proposed to protect tumour cells from apoptosis." (PMID 31910742, 2020). "Immunohistochemistry (IHC) was used to detect CDK5 expression in 54 cases of chronic cervicitis, 42 cases of condyloma acuminate (CA), 38 cases of carcinoma in situ, and 360 cases of cervical cancers [adenocarcinoma, n = 63; squamous cell carcinoma (SCC), n = 263; adenosquamous carcinoma, n = 34]." (PMID 27406233, 2016). "Currently, there are merely two researches on CDK5 in cervical cancer." (PMID 27406233, 2016). "Based on our observations, we speculated that the up-regulated expression of CDK5 from precancerous lesions to cervical cancer tissues might be intimately correlated with the development of cervical carcinoma." (PMID 27406233, 2016). "Therefore, future in vitro and in vivo studies to explore the carcinogenesis mechanism of CDK5 in cervical cancer is warranted." (PMID 27406233, 2016). "We conjectured that the role of CDK5 involved in the proliferation, migration and apoptosis of other tumors cells may provide clues to the ascertainment of its contribution in cervical cancer." (PMID 27406233, 2016). "CDK5 expression in the group with lymph node metastasis (86.5 %) was higher than that in the non-lymph node metastasis group (51.5 %) (P < 0.001), indicating that CDK5 up- regulation may be relative to the carcinogenesis and progression of cervical cancer." (PMID 27406233, 2016).
cervical cancer (continued). "CDK5 may play a vital role in the development of cervical cancer, which may be a marker for the diagnosis, therapy and prognosis of cervical cancer." (PMID 27406233, 2016). "The clinical role of CDK5 in cervical cancer may be better defined with a larger sample size, and a long follow-up prognosis analysis is extraordinarily necessary." (PMID 27406233, 2016). "Importantly, depletion of CDK5 using siRNA sensitized cervical cancer cells to cisplatin." (PMID 31910742, 2020). "And CDK5 may become a new biomarker or molecular target for the treatment of cervical cancer." (PMID 27406233, 2016). "Besides the expression of CDK5 in cervical cancer tissues, we further investigated the correlation between CDK5 expression and clinicopathological factors, which could reflect the deterioration and development of cervical cancer." (PMID 27406233, 2016). "CDK5 may play an essential role in the development of cervical cancer and it may be useful for the clinical diagnosis, treatment and prognosis evaluation of cervical cancer." (PMID 27406233, 2016). "Thus, CDK5 may play consistent oncogenic roles in cervical carcinoma and non-small cell lung cancer." (PMID 27406233, 2016). "The mechanism of CDK5 influencing the lymphatic metastasis remains unknown in cervical carcinoma." (PMID 27406233, 2016). "Our results showed that CDK5 expression level was remarkably higher in cervical cancer tissues (59.8 %) compared with non-cancer tissues (29.2 %) (P < 0.001), indicating that CDK5 up-regulation may be relative to the carcinogenesis and progression of cervical cancer." (PMID 27406233, 2016). "Among them, PLK1, ATM, CDK5 and CHEK1 are abnormally expressed in cervical cancer." (PMID 32655987, 2020). "The expression of CDK5 was lower in non-cervical cancer tissues (29.2 %) compared with cervical cancer tissues (59.8 %) (P < 0.001)." (PMID 27406233, 2016). "But there is no available research about CDK5 expression level and mechanisms in cervical cancer tissues and precancerous lesions." (PMID 27406233, 2016).
leukemia (9 papers, 2012 to 2023). A malignant (clonal) hematologic disorder, involving hematopoietic stem cells and characterized by the presence of primitive or atypical myeloid or lymphoid cells in the bone marrow and the blood. "They argued that Cdk5 activity needed cleavage of pro-enzyme caspase-3 to its active form in cAMP-induced apoptosis of leukemia cells." (PMID 31506563, 2019). "Not only is Noxa stably expressed in lymphocytic leukemias, it is also phosphorylated by the kinase Cdk5 to prevent it from functioning as a canonical death promoter in the leukemia cells." (PMID 26411306, 2015). "Therefore, CDK5-dependent phosphorylation acts as a glucose-sensitive switch that allows NOXA to play either a growth-promoting or proapoptotic role in leukemia." (PMID 37993880, 2023). "Several reports have demonstrated that CDK5 is also important for insulin secretion in pancreatic beta cells, differentiation of myogenic precursor cells, cell-matrix and cell-cell adhesion in lens epithelial cells, and survival of leukemia cells." (PMID 22768111, 2012). "Pathway analysis on 419 unique and mappable genes in the “leukemia correlated cluster” showed enrichment of the following pathways: acute phase response signaling, 1D–myo-inositol hexakisphosphate biosynthesis, hepatic fibrosis/hepatic stellate cell activation, CDK5 signaling, and PAK signaling." (PMID 29506475, 2018). "The proteins levels of CDK5 and its activators have not been analyzed in leukemia specimens to date." (PMID 37993880, 2023).
type 2 diabetes (9 papers, 2013 to 2025). "Here in the present study, we showed that metformin, the most widely used drug for type 2 diabetes, suppressed Cdk5 hyper-activation and Cdk5-dependent tau hyper-phosphorylation in the APP/PS1 mouse hippocampus." (PMID 32670025, 2020). "The ERK/Cdk5 axis also controls PPAR-γ function in type 2 diabetes." (PMID 36678589, 2023). "Accordingly, we suggest that the Cdk5 inhibitor, CIP, may serve as a therapeutic agent for type 2 diabetes." (PMID 24039692, 2013).
colon cancer (8 papers, 2013 to 2023). "Cdk5 has lately been implicated in the formation and progression of several malignancies, including colon tumors." (PMID 36903287, 2023). "Among the upstream regulators (TFs, kinases, and MMTRs) of the DEGs, the expression of STAT3, RPS6KA5, IKBKE, ERBB2, MTOR, and NFKB1 had a positive correlation with OS in colon cancer, while the expression of CDK1, CDK5, and BRD2 had a negative correlation with OS in colon cancer." (PMID 31186640, 2019).
dementia (8 papers, 2014 to 2025). Loss of intellectual abilities interfering with an individual's social and occupational functions. "By overcoming these challenges, studies on tau phosphorylation by Cdk5 can provide valuable insight on the molecular mechanism underlying AD and the development of strategies to prevent dementia." (PMID 25076872, 2014). "Wuqin Jiannao Formulation can significantly inhibit the abnormally high expression of CDK5 in the hippocampus and enhance learning-memory of dementia rats." (PMID 35846430, 2022). "While these drugs may promote dementia through a molecular target unrelated to tau, it remains formally possible that other isoforms of tau (e.g., 4R vs. 3R) phosphorylated by another kinase (e.g., CDK5) may be more responsive to some of these drugs." (PMID 33024171, 2020).
Lissencephaly (8 papers, 2011 to 2024). A spectrum of malformations of cortical development caused by insufficient neuronal migration that subsumes the terms agyria, pachygyria and subcortical band heterotopia. "In fact, patients carrying mutations in genes such LIS1, doublecortin (DCX), and cyclin-dependent kinase 5 (CDK5) show lissencephaly." (PMID 33659245, 2021). "Human patients with classical lissencephaly were often found to have mutations in CDK5 (cyclin-dependent kinase 5) gene." (PMID 33996819, 2021). "Interestingly, lissencephaly with cerebellar hypoplasia has been attributed to individuals with mutations in CDK5 or RELN." (PMID 38596707, 2022). "Cdk5 has been reported to be responsible for human lissencephaly and therefore is thought to be important for cortical folding." (PMID 35386196, 2022). "Studies in Cdk5 KO mice reported various impairments of the brain development, but the link with lissencephaly remained unexplored." (PMID 33996819, 2021). "NUDEL is phosphorylated by Cdk5-kinase and forms a stable complex with lissencephaly-1 and 14-3-3ε." (PMID 21559492, 2011).
osteosarcoma (8 papers, 2013 to 2025). A usually aggressive malignant bone-forming mesenchymal neoplasm, predominantly affecting adolescents and young adults. "Some evidence suggests that, at least in ezrin, Thr235 is phosphorylated by cyclin-dependent kinase 5 (CDK5) and cooperates with Thr576 for its full activation and the cell morphology changes induced in osteosarcoma cells during senescence." (PMID 32098334, 2020). "Reduction of TRAF4 expression promoted inhibitory effects on the proliferative ability of osteosarcoma cell culture; CDK5, member of the family of cyclin-dependent kinases, plays a role in DNA damage response and cell cycle checkpoint activation." (PMID 30908498, 2019). "CDK5 and TWIST1 have been reported to increase metastasis and are upregulated in osteosarcoma tumors with low levels of 14q32 miRNAs." (PMID 23311495, 2013). "Cyclin dependent kinase 5 (CDK5) and Twist Family BHLH Transcription Factor 1 (TWIST1) have been reported to increase metastasis through regulating cell cycle and EMT and they were found to be upregulated in osteosarcoma tumors with low levels of 14q32 miRNAs." (PMID 34066712, 2021).
thyroid cancer (8 papers, 2008 to 2024). "Our results indicate that CDK5 is highly expressed in TT cancer cells relative to other thyroid cancer cell lines." (PMID 34207842, 2021). "We previously found that CDK5 is responsible for thyroid cancer growth through signal transducer and activator of transcription 3 (STAT3) activation." (PMID 31395805, 2019). "Our previous study also showed that CDK5 regulates thyroid cancer cell proliferation through the activation of STAT3 on Ser-727 phosphorylation." (PMID 31395805, 2019). "On the other hand, our previous study demonstrated that CDK5 inhibition reduced tumor formation with phosphorylation of STAT3 on Ser-727, and it has been reported that Her2 is an upstream protein of CDK5 in thyroid carcinoma cells." (PMID 31395805, 2019). "Pharmacological and genetic inhibition of CDK5 has inhibited growth of breast and thyroid cancer cell lines." (PMID 26146988, 2015). "CDK5, a proline-directed serine/threonine kinase, regulates the motility and migration of tumor cells, playing a vital role in the tumor progression and metastasis in thyroid cancer." (PMID 36106120, 2022). "Likewise, the tumoral and proliferative gene set includes the gene for cyclin-dependent kinase 5 (CDK5), which has been shown to regulate cell proliferation in thyroid carcinoma." (PMID 18973659, 2008).
brain tumor (7 papers, 2017 to 2022). "CDK5 appears to be a relevant target for brain tumors because it is highly expressed in the brain and in primary brain tumors but is very rarely mutated, conferring a stable activity and so a potential uniform sensibility to its inhibitor." (PMID 32708903, 2020). "The CDK5 has been reported in the development of various types of human cancers including breast, colon, lung, pancreatic, and brain tumors." (PMID 36590916, 2022). "CDK5 also phosphorylated DRP1 at Ser616 to increase mitochondrial fission in brain tumor initiating cells (BTIC), while Ca2+ calmodulin-dependent protein kinase 2 (CAMK2) phosphorylated DRP1 at Ser637, inducing mitochondrial fusion in non-BTIC tumor." (PMID 33804169, 2021). "Taken together, CDK5 seems to be a corner stone of primary brain tumor growth and survival, increasing interest in drug-development to target this molecule." (PMID 32708903, 2020). "Genetic approaches had shown that Drosophila Cdk5 is overexpressed in Drosophila brain tumor stem cells and regulates asymmetric cell division of neuroblasts as well as tumor growth." (PMID 31488827, 2019). "In brain tumor initiating cells, cyclin-dependent kinase 5 (CDK5)-mediated DRP1 activation drives massive mitochondrial fragmentation, affects AMPK pathway, and correlates with poor prognosis." (PMID 28512624, 2017). "In brain tumours, Drp1 could be catalysed by cyclin‐dependent kinase 5 (CDK5) to maintain self‐renewal and tumour growth by initiating cell mitochondrial fragmentation." (PMID 36200262, 2022).
depression (7 papers, 2015 to 2023). "Our present work indicates a potentially important role of CDK5 in the molecular mechanisms underlying stress response and major depression." (PMID 26057048, 2015). "CDK5 was reported to have an association with depression, but the underlying mechanisms may be complex." (PMID 34035826, 2021). "Although the molecular basis of neuropsychological processes such as depression in HD is only partially understood, recently published results suggest a role of Cyclin-dependent kinase 5 (Cdk5)–related signaling pathway in the NAc in this pathology." (PMID 35269761, 2022). "Accumulating evidence suggests that Cdk5 also plays an important role in the pathophysiology of depression." (PMID 28769056, 2017). "Taken together, these results indicate that CDK5 is an integral component of stress response and major depression with regulatory means specific to different stressors, brain areas and diseases in part through changing phosphorylation of GR." (PMID 26057048, 2015). "We examined potential contribution of CDK5 to stress response and pathophysiology of major depression." (PMID 26057048, 2015). "Our results suggest that acute and chronic stress differentially regulate CDK5 activity/expression in a brain area-specific fashion, which may further contribute to pathophysiology of stress-triggered major depression." (PMID 26057048, 2015). "Since chronic stress is associated with pathophysiology of major depression and GR is a potential target of anti-depressant drugs, we measured CDK5 activity in PFC and HIPPO of postmortem brains of subjects with major depression." (PMID 26057048, 2015). "Through the action of Cdk5 upon dopamine- and cAMP-regulated phosphoprotein 32 (DARPP-32) and the phosphorylation of β-adducin, formation of the dendritic spine cytoskeleton can be affected resulting in the development of depression." (PMID 35269761, 2022). "In the postmortem brains of subjects with major depression, CDK5 activity was elevated in Brodmann's area 25, but not in entire PFC and HIPPO." (PMID 26057048, 2015). "In this study, we found that the p-Cdk5 (Tyr 15)/Cdk5 ratio increased in the PFC and hippocampus of mice with the depression-like phenotype, but not in the NAc." (PMID 28769056, 2017).
Hyperglycemia (7 papers, 2009 to 2025). An increased concentration of glucose in the blood. "Together these findings suggest an NGF/Sirt1 axis where NGF upregulates Sirt1 to maintain autophagy and cell survival, conversely, hyperglycemia-driven Cdk5 activation suppresses NGF, impairing autophagy." (PMID 41471293, 2025). "TFP5, a 25-amino acid peptide inhibiting CDK5 activity, decreased the secretion of inflammation cytokines in serum and kidney, and effectively protected the kidney function in db/db mouse from hyperglycemia-induced kidney injuries." (PMID 35874807, 2022). "In conclusion, TFP5 treatment protects the kidney from hyperglycemia-induced damage by CDK5-NGF-Sirt1 regulation axis, and NGF and Sirt1 may be the novel target for DN." (PMID 35874807, 2022). "Thus, we speculate that chronic hyperglycemia may augment tau hyperphosphorylation through the activation of CDK5, JNK and P38 MAPK signaling and the inhibition of PP2A activity, rather than through GSK3." (PMID 27406855, 2016). "In conclusion, the CDK5-NGF/Sirt1 regulating axis may be the novel pathway to prevent DN progression and TFP5 may be a promising compound to improved hyperglycemia induced DN." (PMID 35874807, 2022).